LECT2 (leukocyte cell derived chemotaxin 2)
Description:
Has a neutrophil chemotactic activity. Also a positive regulator of chondrocyte proliferation. Does not show metalloendopeptidase activity.
Synonyms: chm-II; chm2
Tractability: Antibody: UniProt places it where antibodies can reach, with high confidence; UniProt predicts a signal peptide or a membrane-spanning region; its Gene Ontology location is reachable by antibodies, with medium confidence.
Gene: Protein-coding gene on chromosome 5 (135,922,279 to 135,954,983, reverse strand). Ensembl gene ENSG00000145826.
Subcellular location: Cytoplasm; Secreted
Subcellular location (Human Protein Atlas): Cytosol; Vesicles; Predicted to be secreted
Gene Ontology:
Molecular function: identical protein binding; protein binding
Biological process: chemotaxis; skeletal system development
Cellular component: cytosol; cytoplasm; extracellular region
Genetic constraint (gnomAD): Loss-of-function variants: 6 observed, 11.06 expected, observed/expected ratio (o/e) 0.54, 90% interval 0.3 to 1.07. The upper end of that interval is the gene's LOEUF score, 1.07, which puts it in group 4 of 6, group 1 being the genes least tolerant of losing a copy. Missense variants: 124 observed, 135.08 expected, observed/expected ratio (o/e) 0.92, 90% interval 0.79 to 1.07. Synonymous variants: 40 observed, 46.49 expected, observed/expected ratio (o/e) 0.86, 90% interval 0.67 to 1.12.
Homologues: Orthologues: chimpanzee LECT2 (99% identical), macaque LECT2 (98% identical), dog LECT2 (87% identical), pig LECT2 (85% identical), rabbit LECT2 (84% identical), rat Lect2 (84% identical), mouse Lect2 (83% identical), zebrafish lect2.1 (50% identical), zebrafish lect2.3 (48% identical), zebrafish lect2.2 (46% identical), guinea pig Lect2 (44% identical), Caenorhabditis elegans lect-2 (29% identical).
Diseases named in the same sentence as LECT2 in open-access papers:
LECT2 is named in the same sentence as 87 diseases in open-access papers, as found by Europe PMC text mining. Sharing a sentence is not in itself a finding about the gene and the disease. The quoted sentences say what the papers report.
Obesity (27 papers, 2016 to 2025). Accumulation of substantial excess body fat. "Several human studies have explored the association between circulating LECT2 levels and metabolic disorders, providing valuable insights into its potential role in obesity, NAFLD, insulin resistance, and cardiovascular diseases." (PMID 40284206, 2025). "LECT2 was first recognized as a chemotactic factor for neutrophils and later reidentified as a hepatokine linked to obesity." (PMID 40284206, 2025). "All of them are from Kanazawa University, and their research on LECT2 is biased toward the association of LECT2 with obesity and insulin resistance." (PMID 38881894, 2024). "The present study investigated the dynamics in the blood levels of SeP and LECT2 during weight loss after laparoscopic sleeve gastrectomy (LSG) in patients with severe obesity." (PMID 37957316, 2024). "In mammals, LECT2 is known as a hepatokine mediating obesity with insulin resistance and associated with the inflammatory response." (PMID 31480179, 2019). "This means LECT2 plays an important role in the regulation of insulin sensitivity, and it may provide a novel perspective for the therapy of obesity‐associated insulin resistance." (PMID 35656863, 2022). "LECT2 may be a therapeutic target for obesity‐associated insulin resistance." (PMID 35656863, 2022). "Therefore, LECT2 may be associated with metabolic disturbances and unfavorable clinical consequences in individuals with obesity and NAFLD." (PMID 28376109, 2017). "LECT2 is upregulated in response to overnutrition, and its circulating levels are significantly higher in patients with obesity and NAFLD." (PMID 40284206, 2025). "Previous observations indicate a general increase in chemerin and LECT2 levels in obesity and IR states." (PMID 39138826, 2025). "Leukocyte cell-derived chemotaxin 2 (LECT2) is upregulated in the livers of people with obesity by sensing liver fat." (PMID 37957316, 2024). "Regarding obesity and insulin resistance, overexpression of LECT2 reduces insulin receptor substrate (IRS-1) levels." (PMID 38881894, 2024). "Other hepatokines such as fetuin-A, hepassocin, LECT2 (leukocyte cell-derived chemotaxin-2), and selenoprotein are commonly increased in obesity and result in the systemic inflammatory state." (PMID 39335642, 2024). "Another study revealed that LECT2 acts as a hepatokine connecting obesity with insulin resistance in skeletal muscle." (PMID 38881894, 2024). "Circulating LECT2 levels are highly sensitive to the change in fat content, and positively correlated with the severity of obesity, NAFLD, IR, hepatic steatosis and inflammation." (PMID 37180779, 2023). "Conversely, LECT2 knockout mice are strongly protected from developing obesity and liver inflammation following high-fat diet feeding." (PMID 37755259, 2023). "LECT2 also targets skeletal muscle and causes insulin resistance by activating the c-Jun N-terminal kinase (JNK) pathway in obesity." (PMID 37755259, 2023). "Nasr and co-authors report that plasma LECT2 concentration in normal individuals is 19.7 ± 3.4 ng/mL and generally rises in liver diseases, obesity, and insulin resistance." (PMID 38137613, 2023). "Circulating levels of AHSG, ANGPTL4 and LECT2 were previously demonstrated to correlate with obesity, BMI or waist circumference in humans." (PMID 35409319, 2022). "Recent studies found positive correlations between serum levels of LECT2 and obesity, the severity of liver steatosis and IR in both mouse models and humans." (PMID 36267567, 2022). "Serum LECT2 levels presented a close correlation with the severity of both obesity and insulin resistance in human." (PMID 35656863, 2022). "LECT2 is a novel obesity‐related protein and serum LECT2 levels are increased by obesity and fatty liver." (PMID 35656863, 2022). "Recent studies found that serum levels of LECT2 positively correlate with measures of obesity, the severity of liver steatosis and IR in both mouse models and humans." (PMID 36267567, 2022).
Obesity (continued). "The main hepatokines related to insulin resistance, a fundamental factor in the development of DM2 and obesity, are fetuin-A, hepassocin, LECT2, and selenoprotein." (PMID 33807959, 2021). "In the present study, we demonstrated that LECT2 is a hepatokine that links obesity to hepatic inflammation via activation of LPS signaling in macrophages." (PMID 33436955, 2021). "In humans, the circulating LECT2 is correlated with the severity of both obesity and insulin resistance." (PMID 30406127, 2018). "Serum LECT-2 levels are increased in patients with obesity and fatty liver disease, suggesting that LECT-2 is a novel obesity-related protein." (PMID 29910974, 2018). "Furthermore, circulating LECT2 concentrations were greater in subjects with MetS (32.6 [17.8, 45.0] vs. 27.0 [18.7, 33.7] ng/ml, P = 0.016) and were associated with anthropometric measures of obesity, lipid profiles, high sensitivity C-reactive protein (hsCRP) and liver aminotransferase levels." (PMID 28376109, 2017). "LECT2 is a recently discovered hepatokine that contributes to the development of skeletal muscle insulin resistance in obesity." (PMID 28376109, 2017). "Leukocyte cell-derived chemotaxin 2 (LECT2) is a hepatokine linking obesity to skeletal muscle insulin resistance." (PMID 28278265, 2017). "LECT2 functioned as a hepatokine connected to obesity through the induction of insulin resistance in skeletal muscle." (PMID 28025491, 2016). "Recently, a DNA chip analysis from liver biopsies of patients with type II diabetes showed a positive correlation between the hepatic LECT2 expression level and BMI, describing a relationship between LECT2 and obesity." (PMID 28025491, 2016). "LECT2 positively correlated with miR-122-5p and miR-151a-3p, paralleling its significant levels in MASLD individuals with metabolic syndrome components and associations with obesity and anthropometric measures." (PMID 39138826, 2025). "Moreover, circulating LECT2 levels are positively correlated with the progression of obesity and NAFLD in humans." (PMID 40284206, 2025). "Among immune system diseases like osteoarthritis and rheumatoid arthritis, septicemia, atherosclerosis, osteoporosis, diabetes, atopic dermatitis, epithelial ovarian cancer, and obesity, LECT2 can activate and recruit immune cells to regulate inflammatory responses and immune responses." (PMID 38881894, 2024). "Similarly, LECT2 mediates obesity-related metabolic disturbances, and its downregulation ameliorates hepatic steatosis." (PMID 38892481, 2024). "Interestingly, LECT2-deficient mice exhibited increased insulin sensitivity in skeletal muscle rather than in liver or adipose tissue, but muscle insulin sensitivity of LECT2-deficient mice was attenuated by a high-fat diet, indicating that LECT2 may be a therapeutic target for obesity-induced IR." (PMID 37180779, 2023). "LECT2 exhibited a close correlation with obesity and obesity‐related liver diseases in both males and females, and it could draw a clear distinction between the subjects with or without fatty liver." (PMID 35656863, 2022). "Collectively, as a novel obesity‐related protein, LECT2 might directly participate in the inflammatory reactions in human endothelial cells." (PMID 35656863, 2022). "LECT2 acts directly on skeletal muscle by positively correlating insulin resistance and obesity." (PMID 36362238, 2022). "Therefore, LECT2 can be an important marker to explain how the fatty liver leads to insulin resistance in obesity since its deletion of LECT2 increases insulin sensitivity in skeletal muscle in rats." (PMID 33807959, 2021). "Although previous studies reported that obesity was associated with high levels of circulating LECT2 in human, the associations of detailed body fat distribution with LECT2 levels have not been examined." (PMID 28278265, 2017).
Obesity (continued). "Moreover, FABP4 gene expression was negatively correlated with BW and fat mass, whereas LECT2 gene expression was positively correlated with obesity and insulin resistance." (PMID 28924246, 2017). "LECT2 is also positively correlated with diet-induced weight cycling in mice and humans, suggesting that LECT2 is a sensing hepatokine for nutritional regulation-mediated metabolic homeostasis and functions as an indicator for management of obesity in the clinic." (PMID 36969200, 2023). "Indeed, increased liver production of LECT2 have been related to obesity development in rats, and resulting metabolic stress, which subsequently impairs insulin signaling, promote adhesion molecules expression, and increases pro-inflammatory cytokines synthesis." (PMID 34822062, 2022). "Researchers have also found that LECT2 is involved in many other pathological conditions, such as obesity, skeletal muscle insulin resistance, non-alcoholic fatty liver disease, and metabolic syndrome, thus suggesting the potential role of LECT2 in atherosclerosis." (PMID 31310065, 2019). "Leukocyte cell-derived chemotaxin 2 (LECT2) is a recently discovered hepatokine that plays crucial roles in various diseases, such as obesity, T2D, liver fibrosis, and hepatocellular carcinoma." (PMID 37755259, 2023). "In addition to SeP and LECT2, these hepatokines and metabolic disorders are complexly intertwined; therefore, the measurement and activity of hepatokines may help to identify a deeper mechanism of accelerating metabolic disorders in patients with severe obesity." (PMID 37957316, 2024). "Although the potential therapeutic relevance of modulating the expression/activity of AHSG, ANGPTL4, LECT2 and FGF21 for treating obesity, IR and liver metabolic disorders is still unclear, targeting these hepatokines appears to be a promising strategy in addition to other currently used therapies." (PMID 35409319, 2022). "In contrast, while the expression of Fetub and Lect2 ws found to be decreased in LPTENKO mice, these hepatokines are frequently upregulated in mouse models and patients with obesity, steatosis and IR, supporting a potential important role for these hepatokines in LPTENKO mice." (PMID 35409319, 2022). "Although LECT2 has been suggested to play a role in obesity-induced insulin resistance, our cross-sectional study in Japanese men demonstrated that HOMA-IR was not independently associated with plasma LECT2 levels." (PMID 28278265, 2017). "However, the role of LECT2 in the development of obesity and insulin resistance induced by over-nutrition has not yet been established." (PMID 28924246, 2017).
Insulin resistance (23 papers, 2017 to 2025). Increased resistance towards insulin, that is, diminished effectiveness of insulin in reducing blood glucose levels. "A Japanese study utilizing health check-up data reported a positive association between circulating LECT2 levels with both adiposity and the severity of insulin resistance in humans." (PMID 40284206, 2025). "Human LECT2 is associated with inflammation and insulin resistance and the suppression of inflammatory and immune responses by LECT2 can inhibit tumorigenesis in liver." (PMID 31480179, 2019). "Progression of insulin resistance and serum concentration of LECT2 were determined to be the likely mechanisms of HF diet–induced loss of muscle mass and the effects of GTEs against HF diet induced–insulin resistance and muscle atrophy." (PMID 29630667, 2018). "Previous studies have shown that leukocyte cell-derived chemotaxin 2 (LECT2), a recently discovered hepatokine, is associated with the inflammatory response and insulin resistance." (PMID 28376109, 2017). "Several studies have associated LECT2 with glucose metabolism, insulin resistance and inflammation." (PMID 32998709, 2020). "Accordingly, GTEs might have beneficial effects on age-related and HF diet–induced muscle weight loss, which correlates with insulin resistance and is accompanied by a change in serum LECT2." (PMID 29630667, 2018). "Fei Lan, Okumura A and Tae Woo Jung proposed that LECT2 is a metabolism-related hepatokine, and predicted it as a therapeutic target for insulin resistance, respectively." (PMID 38881894, 2024). "LECT2 stimulates inflammatory response and insulin resistance in adipocytes via CD209/P38 dependent pathway." (PMID 35656863, 2022). "Gemigliptin, a dipeptidyl peptidase‐4 (DPP‐4) inhibitor, was able to relieve hepatic steatosis and insulin resistance by suppressing LECT2 expressions involved in increased AMPK phosphorylations in HFD‐fed mice." (PMID 35656863, 2022). "It has been reported high fatty diet induces inhibition of AMPK pathway and hepatic LECT2 overproduction, which increases the circulating LECT2 to promote insulin resistance in muscle." (PMID 36055405, 2022). "In mice, HFD enabled the increase in the levels of LECT2, and the overproduced LECT2 further impaired insulin sensitivity and induced insulin resistance in skeletal muscle cells." (PMID 35656863, 2022). "Identification of the interaction partners in the skeletal muscle is necessary to gain insights into the role of LECT2 in the development of insulin resistance." (PMID 32764719, 2020). "Although our study did not directly show the effect of serum LECT2 on muscle weight, insulin resistance examined using HOMA-IR indicated an intervention effect of serum LECT2 on muscle weight, as revealed by partial correlation analysis." (PMID 29630667, 2018). "Lect2 deletion attenuates muscle insulin resistance in dietary obese mice, and Lect2 transfection in myocytes decreases insulin signaling." (PMID 29630667, 2018). "Other studies have suggested that LECT2 also affects adipose tissue insulin resistance." (PMID 38137613, 2023). "Gemigliptin might alleviate hepatic steatosis and insulin resistance by supressive LECT2 expression." (PMID 35656863, 2022). "Fortunately, Gemigliptin, a novel DPP‐4 inhibitor, could efficiently inhibit LECT2 expressions, improve hepatic steatosis and ameliorate insulin resistance by increasing AMPK phosphorylation and reducing CD209 receptor‐mediated JNK pathway." (PMID 35656863, 2022). "Therefore, LECT2 induces insulin resistance in the skeletal muscle and sarcopenic obesity observed in obese individuals with type 2 diabetes." (PMID 32764719, 2020). "Identification of the LECT2 receptor in the skeletal muscle can provide detailed insights into the mechanisms linking obesity with the pathogenesis of insulin resistance in the skeletal muscle, which facilitates the development of LECT2-targeted agents for the treatment of insulin resistance." (PMID 32764719, 2020).